TNF (tumor necrosis factor)
Diseases named in the same sentence as TNF in open-access papers (continued):
Sharing a sentence is not in itself a finding about the gene and the disease.
diabetes (continued). "Consistent hyperglycemia in diabetes induces activation/inhibition of diverse pathways, including polyol, hexosamine, AGEs, PARP, MAPK, mTOR, NF-κB and tumor necrosis factor-α (TNF-α) pathway, which contribute to the pathogenesis and progression of DN." (PMID 37920252, 2023). "measured the levels of pro-inflammatory tumour necrosis factor-alpha (TNFα), anti-inflammatory interleukin-10 (IL-10), DICER, and miRNAs in hearts of Akita, a genetic mice model for diabetes, and C57BL/6J (WT)." (PMID 36950696, 2023). "CRP: c-reactive protein; IL6: interleukin 6; MDA: malondialdehyde; SUA: serum uric acid; T2DM: type 2 diabetes mellitus; TAC: total antioxidant capacity; TNF-α: tumor necrosis factor-alpha." (PMID 38034261, 2023). "We observed that pro-inflammatory cytokines such as TNF-α, IL-6, and IL-1β were increased following HFD-induced diabetes." (PMID 35928902, 2022). "In diabetic patients, there is a greater role of inflammation for developing diabetes complications, such as hs-CRP, Interleukin-1 and -6, TNF-α, and expression of specific miRs, belonging to a family of small non-coding RNAs." (PMID 35458670, 2022). "It has also been shown that APS can reduce TGF-β1 and TNF-α expression, increase SOD activity, reduce MDA content, reduce myocardial oxidative stress and fibrosis, and reduce diabetes-induced myocardial injury in DCM rats." (PMID 35322740, 2022). "Compared with previous studies, we evaluated immunologic indices, including IL-6, TNF-α, IL-4, IL-10, TGF-β1 levels, and regulatory T cells, in addition to general diabetes evaluation." (PMID 35725652, 2022). "It was also found that the TNF, PI3K/Akt, and MAPK signal pathways can interact with the HIF signal pathway, leading to the gradual progress of diabetes and its complications." (PMID 35990823, 2022). "Empagliflozin diminished the renal expression of inflammatory markers (TNF-α, MCP-1) by acting on the HMGB1-TLR4 axis in an experiment involving rats with streptozocin-induced diabetes." (PMID 36362984, 2022). "This research proved significant variations of adiponectin, nesfatin-1, IL-6, and TNF-α levels in the healthy, prediabetics, and T2DM, suggesting a slow and gradual change during the progression from a healthy condition toward diabetes via prediabetes." (PMID 35311231, 2022). "BAT1 was identified as an anti-inflammatory gene through the modulation of pro-inflammatory cytokines tumor necrosis factor-alpha (TNF-α), interleukin-1 (IL-1), and interleukin-6 (IL-6) in diabetes, Chagas cardiomyopathy, and Plasmodium vivax malaria." (PMID 36505884, 2022). "Diabetes triggered NLRP3, ASC, gasdermin-N, caspase-1, and collagen I expression in myocardial tissue, and promoted an increase in the serum TNF-α, IL-1β, IL-6, and IL-18 levels." (PMID 36320147, 2022). "In multivariate logistic regression models with SHR >1.14 as the dependent variable, log IL-10, IL-10/TNF-α ratio, log CXCL10, and log IFN-γ were separately included together with age, sex, presence of diabetes, CRP, and severity of disease as covariates." (PMID 36059840, 2022). "The role of pro-inflammatory cytokines, such as IL-1β and TNF-α, in the mediation of chronic inflammation and disruption of the BRB has been well documented in several animal models of diabetes and DR." (PMID 36139465, 2022). "In monocytes exposed to TNF-α, SET7/9 deletion not only inhibits inflammatory genes, including TNF-α, MCP-1 and IL-6, but also attenuates diabetes-induced inflammatory processes." (PMID 35883538, 2022). "This proposed link was further reinforced by the elevation of periodontal parameters and TNF-α levels, which substantiate the relationship between periodontal disease and progression of CKD, with diabetes as one of the confounding factors." (PMID 35336824, 2022).
diabetes (continued). "Rather, sustained STING expression in diabetes is detrimental to wound healing due to decreased Mφ-mediated IFN-I production and increased IL-1β, TNF-α, and IL-6 production, all of which act in concert to sustain a proinflammatory Mφ phenotype." (PMID 36127466, 2022). "Decreased muscle strength is related to increased levels of inflammatory markers (tumour necrosis factor-alpha (TNF-α), interleukin-6 (IL-6), and C-reactive protein (CRP)), which can induce the development of diabetes." (PMID 36010223, 2022). "ELISA assays showed that the injection of tRF‐1020 mimics alleviated diabetes‐induced retinal inflammation as shown by decreased expression of VEGF, interleukin (IL)‐2, and TNF‐α." (PMID 36128646, 2022). "These targets are enriched in multiple pathways related to type 2 diabetes mellitus, including adipocytokine, AMPK, TNF, HIF-1, PI3K-AKT, NOD and TOLL-like receptors, mTOR, glucagon, and insulin signaling pathways." (PMID 36160451, 2022). "An analysis of GLP-1 receptor antagonists versus standard diabetes therapies or placebo revealed significant reductions in CRP, TNFα, and malondialdehyde, and significant increases in adiponectin." (PMID 36362984, 2022). "The increasing IL-6, IL-1α, TNF-α and TGF-β expression in the lungs of diabetic rats indicates that the expression of proinflammatory cytokines was upregulated in diabetes and was downregulated by insulin and Rb1 treatment." (PMID 36367996, 2022). "After comparing the diabetes related targets of GQD with cell proliferation targets, 4 potential targets (PPARG, TNF, INSR, CDK4) were selected for GQD." (PMID 35858880, 2022). "Treatment of valproic acid for 8 weeks significantly attenuated diabetes-induced expression of p21 and the SASP markers Il-6, TNF-α, EGFR and Fn." (PMID 36434087, 2022). "Next, we assessed the association between high levels of triglycerides, low levels of HDL-C and heart attack in those with diabetes in presence of pro-inflammatory markers (IL6, TNFα)." (PMID 33510184, 2021). "The role of TNF-α is also studied in atherosclerosis and type 2 diabetes mellitus (DM)." (PMID 33671607, 2021). "Under the conditions of diabetes, LCN2 from satellite glial cells mediates macrophage infiltration into DRG, stimulates the release of inflammatory cytokines such as tumor necrosis factor-α, and enhances neuronal inflammatory response." (PMID 34636748, 2021). "Diabetes patients’ recorded increased levels of OPG, RANKL, TNF-α, MMP-9, IL-18 and TOS compared to controls both pre- and post-extraction." (PMID 34829612, 2021). "The diabetes-induced elevation of angiogenic and inflammatory factors VEGF and TNF-α were also suppressed by pinacidil." (PMID 33523201, 2021). "There was a significant rise in TNF-α, dense fibrosis, and collagen deposits in the STZ diabetes group." (PMID 34512937, 2021). "It was suggested that periodontal curettage combined with root planing therapy can effectively reduce the levels of TNF- α and hs-CRP in patients with type 2 diabetes mellitus complicated with moderate-to-severe chronic periodontitis." (PMID 33832490, 2021). "We also observed inflammatory markers (IL-8, TNF-α and CCL2) protein expression was positively correlated with SRA1 protein expression in individuals with diabetes." (PMID 34685582, 2021). "The major finding of this study was that rats with diabetes in the ECMO model showed rapidly increased inflammatory cytokines, such as TNF-α and IL-6, and other measurements, such as AST, ALT, LDH and L-FABP." (PMID 33920465, 2021). "Research shows that in diabetes, the abnormally differentiated vascular endothelia cells and perivascular macrophages may show an exaggerated inflammatory response characterized by an in-creased secretion of pro-inflammatory cytokines, such as TNF-α, IL-1β and iNOS." (PMID 33918576, 2021).
diabetes (continued). "Inulin supplementation at 10 g/day in patients with type 2 diabetes mellitus has demonstrated the ability in decreasing weight and BMI with significant decreases in serum high sensitivity-CRP, TNF-α, and LPS." (PMID 34376241, 2021). "Further, digoxin that targets TNF and ceritinib that inhibits INSR are found to be potential drugs to manage COVID-19 patients having pre-existing diabetes." (PMID 34067609, 2021). "A shift of T-helpers toward Th1 and Th17 is seen in DKD (type 2 diabetes mellitus), and the concentration of these cells and their cytokines (IL-17, IFN-γ, and TNF-α) in the blood corresponds with albumin levels in urine and blood creatinine." (PMID 34768884, 2021). "Diabetes related biomarkers: GIP, GLP-1, leptin, glucagon and inflammatory cytokines: IL-4, IL-5, IL-10, IL-12, IFN-g and TNF-α were significantly affected by HFB diet compared to HF diet." (PMID 34441468, 2021). "TNF- α and CRP are commonly used inflammatory markers in clinic and are positively correlated with the pathogenesis of diabetes." (PMID 33832490, 2021). "On the other hand, it has been proved that the increased cytokine production by Th1 (IFN-γ, IL-2, TNF-α, and TNF-β) and Th17 (IL-6, IL-17A, and IL-17F) in diabetics can affect the HbA1c level." (PMID 33746897, 2021). "Notably, among current diabetes treatment options used in our study; 10 mg/kg CurNPs and 50 mg/kg ZnONPs exhibited more anti-inflammatory power and showed significant suppression of expression levels of TNF-α, IL-1β as well as iNOS concentration in liver and pancreas." (PMID 34667196, 2021). "The results of this study showed that diabetes induction increased BW, FBG, TG, LDL-C, leptin, and TNF-α levels, and decreased insulin compared to the beginning stage." (PMID 34039404, 2021). "Its mode of action is by attenuating ROS-induced diabetes through the impairment of NF-κB-related proinflammatory cytokines, specifically interleukins, MCP-1, and TNF-α." (PMID 32148647, 2020). "In conclusion, R. tuberosa L hydroethanolic root extracts have beneficial results on diabetes and its accompanying complications, in particular in diabetic nephropathy, through a significant decrease in the levels of kidney MDA and the TNF alpha expression." (PMID 33110487, 2020). "Participants who developed diabetes at the 3-year follow-up (n = 28) had shorter LTL and higher levels of TNF-α and SOD activity at baseline." (PMID 32215181, 2020). "Low-grade systemic inflammation accompanies diabetes, with high serum levels of C-reactive protein (CRP), tumor necrosis factor (TNF-α), monocyte chemo-attracting protein-1 (MCP-1) and IL-1β." (PMID 32903730, 2020). "Administering ALA for 4 months to patients with type 2 diabetes mellitus on the background of basic therapy contributes to a significant reduction in CRP by 30.9%, IL-6 by 29.7%, and TNF-α by 22.7%." (PMID 32341698, 2020). "According to these results, the most important pathways related to treating of diabetes by SQC are PI3K-Akt, HIF-1, TNF, insulin resistance, FoxO, MAPK, AMPK, and insulin signal pathways." (PMID 32595730, 2020). "For example, an animal study conducted on streptozotocin-induced diabetes mice demonstrated a decreased AGE level in urine and kidney as well as plasma TNF-α and reduced renal damage after KRG administration." (PMID 32025522, 2020). "Treatment with LPLI significantly decreased diabetes-induced high mobility group box 1 (HMGB1) and tumor necrosis factor alpha (TNF-α) expression, while enhancing the activation of the transcriptional factor cAMP response element binding (CREB) protein." (PMID 32750068, 2020). "Apart from microglia, diabetes induces the secretion of vascular endothelial growth factor (VEGF) and TNF-α by Müller glia which further aggravates the progression of DR." (PMID 33240260, 2020). "Importantly, INU treatment could decrease TNF-α and IL-6 but increase IL-10 in diabetes mice." (PMID 33390939, 2020).
diabetes (continued). "The older patients more often had diabetes, gastro-intestinal, cardiovascular and other comorbidities and less often used MTX or thiopurine therapy compared with younger patients with anti-TNF therapy (87.8% versus 96.1%, p < .010)." (PMID 32860081, 2020). "Therefore, our findings suggested that dietary intake of non-α-Toc might contribute to the delaying onset of diabetes and related metabolic disorders via suppression of the level of TNF-α in prediabetic individuals, which however, needs to be further validated by mechanistic studies." (PMID 32509152, 2020). "For example, cytokines such as interferon gamma (IFNɣ), interleukin 1 beta (IL1β) and tumor necrosis factor alpha (TNFα; also known as TNF) can drive beta (β) cell dysfunction, damage and death in diabetes mellitus." (PMID 32457041, 2020). "Similar results were observed when we replaced diabetes with inflammatory markers (i.e., C-reactive protein [CRP], tumor necrosis factor alpha [TNF-α], interleukin-6 [IL-6], and monocyte chemoattractant protein-1 [MCP-1]) or serum albumin concentration." (PMID 32661200, 2020). "Diabetes + STD rats showed that the mRNA expression of type 3 collagen (Col3), Kim-1, Cd68 and tumor necrosis factor-α (Tnf-α) in the renal cortex was significantly increased compared to that in the control." (PMID 32145700, 2020). "The increased risk of carotid abnormalities attributable to anti-GRP78 autoreactivity persisted despite adjustment for age, smoking extent, hypertension, diabetes, hyperlipidemia, or levels of CRP, IL-6, and TNF-α." (PMID 32086320, 2020). "As expected, diabetes significantly increased inflammatory markers such as, HMGB1 and TNF-α in SMG, as well as the receptor RAGE with a tendency of increase in the activation of the transcriptional factor NFκB." (PMID 32750068, 2020). "In this study, we showed that STZ-induced diabetes resulted in DR, and 12 weeks of LTF treatment ameliorated retinal damage, delayed DR occurrence, and significantly decreased the expression of TNF-α, IL-1β, MCP-1, and ICAM-1." (PMID 31956338, 2020). "On the contrary, PPARα overexpression in rats with streptozotocin(STZ)-induced diabetes reduces vascular leakage and retinal inflammation by decreasing adherent leukocytes and expression levels of VEGF, TNF-α, and ICAM-1." (PMID 33291567, 2020). "AGE-RAGE (diabetes), HIF-1, PI3K-Akt, and TNF signaling pathways are responsible for the therapeutic effects on DN." (PMID 33178322, 2020). "In this case report, we described for the first time the differential expression of TNF-α, IL-1β, IL-6, and IFN-γ in a blood sample that was taken from a 27-year-old patient with type 1 diabetes mellitus (T1DM) who was diagnosed with HU." (PMID 33375551, 2020). "Neurological degeneration was also significantly improved, accompanied by decreased levels of inflammatory factors (TNF‐α, 57.8%; IL‐1β, 51.4%; IL‐6, 62.8%; and MDA, 40.7% reduction rate against the diabetes mellitus + normal saline group)." (PMID 33215875, 2020). "Significant increases in the value of TNF alpha expression and malondialdehyde (MDA) levels were observed in streptozotocin-induced diabetes rats." (PMID 33110487, 2020). "Induction of diabetes in old rats resulted in significant increase in SBP, aortic PWV, renal artery resistance, and serum levels of ET1, ANG II, IL-6, TNF-α, MDA, ROS, and VEGF." (PMID 32426041, 2020). "AdipoRon decreased diabetes-induced transcription of proinflammatory cytokines, such as IL-6, MCP-1, and TNFα in the kidney of db/db mice." (PMID 32832003, 2020). "We show that diabetes leads to higher systemic levels of LTB4, IL-6 and TNF-α in cutaneous leishmaniasis." (PMID 32525457, 2020). "Studies in adults have shown a strong relationship of certain metabolic diseases, for example, diabetes, with elevated levels of CRP, TNF-α, and leptin." (PMID 33081030, 2020).
diabetes (continued). "In diabetes, PLEK has been reported to promote the secretion of proinflammatory cytokines such as TNF-α and IL-1β in mononuclear phagocytes; these cytokines have already been linked to increased risk of UC and RA." (PMID 33262784, 2020). "Animal study and human studies have found that diabetes could accelerate the appearance of cerebrovascular inflammation and Aβ deposition, as evidenced by increased levels of proinflammatory cytokines such as interleukin (IL-6) and tumor necrosis factor (TNF-α)." (PMID 31296192, 2019). "TNF-α, IL-6, and MMP-9 were significantly upregulated in traumatized skin of rats with STZ-diabetes than in normal trauma rats (NC group) (p < 0.05)." (PMID 31605256, 2019). "Inflammation contributes to the pathogenesis of diabetes, in which SAA and other inflammatory markers, including CRP, TNF, and MCP-1, increase in parallel with urinary albumin." (PMID 30899260, 2019). "By contrast, DNP induces upregulation of TNF-α and CXCR4 in the DRG at both the early phase and the late phase of diabetes." (PMID 31001066, 2019). "Multivariate linear regression was performed to study the interaction of PTX3 with age, gender, smoking history, family history of cerebrovascular disease, BMI, level of TNF-α, CHOL, TG, HDL, hs-CRP, hypertension, diabetes mellitus, and history of statin use." (PMID 31998222, 2019). "Present study showed that pro-inflammatory markers i.e., TNF-α, IL-1β, and IL-6 together induce chronic inflammation condition to promote CAD in diabetes." (PMID 30674322, 2019). "Regarding the mechanisms involved in the beneficial effect of the SOCS1 peptidomimetic, we found that it reduces the upregulation of IL-1β, IL-6, TNF-α, and VEGF induced by diabetes." (PMID 31344857, 2019). "It is most likely that the main mechanisms of anti-diabetes involve suppressing TLR2 signalling pathway, stimulating the insulin signalling pathway and the interactions of the two through TNF-α based upon the bioactive compounds identified from WEM." (PMID 31752797, 2019). "As compared with controls and after adjustment for age, sex and diabetes mellitus, sVCAM-1, E-selectin, thrombomodulin, hs-CRP, SAA, IL-6, and TNF-α were higher in CKD5-ND, CKD5-HD and CKD5-PD." (PMID 31518378, 2019). "The first top hubs of Type 1 Diabetes Mellitus and CD networks were insulin (INS) and tumor necrosis factor (TNF), respectively." (PMID 32099612, 2019). "Administration of anti-TNF-α treatment at 4 weeks of age or later contributed to the accelerated progression of T1D, while the systemic administration of TNF-α protected against diabetes." (PMID 31049023, 2019). "Many studies have shown that proinflammatory cytokines including TNF-α, IL-6, IL-1β, CRP, and NF-κB can lead to IR and the development of related diseases such as metabolic syndrome and diabetes, either alone or in combination, via various pathways." (PMID 31218568, 2019). "The inhibition of the diabetes-induced upregulation of PKC-β, TNF-α and VEGF induced by diabetes seems to play an important role in the beneficial vascular action of bosentan." (PMID 30428543, 2018). "Genes related to cardiac remodeling of TGFβ, TNFα and MMP2 were elevated by either diabetes or AT and were reduced in CR-mice." (PMID 30071860, 2018). "We also tested the correlation between TGF-β1 and TNF serum levels and echocardiographic parameters and BNP after excluding all patients with hypertension, diabetes, and any history of coronary artery disease." (PMID 29513876, 2018). "Increased pro-inflammatory factors, interleukin-1β (IL-1β) and tumor necrosis factor-α (TNF-α), exacerbate tissue damage during diabetes via the recruitment of leukocytes to affected tissues." (PMID 30470798, 2018). "In diabetics, the systemic levels of LTB4, TNF-α, IL-6, IL-10, IL-12 and IFNγ were increased as well as the frequency of pro-inflammatory monocytes (CD11b+Ly6ChighLy6G−) compared to healthy mice." (PMID 30242286, 2018).